IL6 (interleukin 6)
Diseases named in the same sentence as IL6 in open-access papers (continued):
Sharing a sentence is not in itself a finding about the gene and the disease.
colorectal cancer (continued). "In colorectal cancer a HIF-1α/miR-338-5p/IL-6 feedback circuit mediates hypoxia induced-drug resistance by increasing the secretion of IL-6 and subsequently activating the IL-6/STAT/Bcl-2 pathway resulting in decreased levels of cleaved-caspase three under hypoxic conditions." (PMID 34869315, 2021). "To determine whether PRKAR2A regulates STAT3 activation through IL-6, we transiently transfected human colorectal cancer cell line RKO with specific PRKAR2A small interfering RNA (siRNA) or control siRNA, and a clear knockdown of PRKAR2A was achieved." (PMID 34349238, 2021). "Thus, combined with our present findings, both IL-6 and autophagy are potential targets for chemotherapy resistance in colorectal cancer." (PMID 34131122, 2021). "As colorectal cancer progression involves MMP-2/9 activity that is up-regulated by IL-6, we first analyzed whether the treatment with rIL-6 alone or after the LPE pretreatment could affect the gelatinase activity in T88 and T93 cells." (PMID 34885656, 2021). "In addition, both SPINK1 and IL-6-induced SPINK1 expression augmented cell motility by regulating STAT3 signaling in colorectal cancer." (PMID 33916984, 2021). "IL-6 in tumor cells and colorectal cancer patients is up-regulation." (PMID 34863141, 2021). "Reportedly, IL-6 secreted by colorectal cancer-derived MSCs could activate JAK2/STAT3 signaling and promote the progression of colorectal cancer." (PMID 34789315, 2021). "Moreover, the IL-6-induced increase in pSTAT3 in the context of knocked down MLKL expression was also found in colorectal carcinoma HT-29 cells." (PMID 33767595, 2021). "As a pro-inflammatory cytokine, IL-6 has a marked effect on the microenvironments of a wide range of cancers, and the level of IL-6 could predict the progress and poor prognosis of colorectal cancer." (PMID 32653013, 2020). "Furthermore, adipocytes also can produce polypeptide hormones (e.g., adiponectin and leptin), TNF-α, IL-6 and free fatty acid to mediate inflammatory response in colorectal cancer." (PMID 31963221, 2020). "The IL6/JAK/STAT3 pathway was reported to promote the metastasis of colorectal cancer." (PMID 32850443, 2020). "In addition, colorectal cancer metastasis signalling, IL-6 signaling, and IL-8 signaling also were also predicted to be activated during EC metastasis, whereas RhoGDI signaling pathway was predicted to be inhibited in metastatic EC." (PMID 32315343, 2020). "Furthermore, IL-6 in colorectal cancer and ovarian cancer ascites with a high concentration of IL-6 has been shown to polarize M2 macrophages." (PMID 32865617, 2020). "Moreover, mechanistic studies have established that IL-1β, IL-6, and TNFα are involved in colorectal cancer progression and that expression of these cytokines is regulated by vitamin D." (PMID 32425932, 2020). "Apart from that, interleukin 6 (IL-6) is a pro-inflammatory cytokine and its overexpression is relevant to numerous types of cancers, such as gastrointestinal cancer, head and neck carcinomas, and colorectal cancer." (PMID 32230808, 2020). "Moreover, IL-6-dependent activation of STAT3 was found to directly repress the miR-34a gene in colorectal cancer cells." (PMID 33371368, 2020). "Notably, IL-6 has immunosuppressive properties in colorectal cancer cells through the recruitment of immune-suppressive cells and reduction of T cell infiltration in cancer tissues." (PMID 33096896, 2020). "Coincidently, IL-1β and IL-6 also participate in colorectal cancer." (PMID 32670290, 2020).
colorectal cancer (continued). "This interaction may induce an increase of IL-6 in a feed-forward loop involving miRNA–miRceptor interactions which are responsible for the increased secretion of IL-6, a typical phenomenon in the colorectal cancer microenvironment." (PMID 30884898, 2019). "The Janus kinase (JAK) inhibitors could inhibit tumor growth in gastric and colorectal cancer via suppressing the IL-6/JAK2/signal transducer and activator of transcription 3 (STAT3) pathway and enhancing the secretion of anti-tumor cytokines." (PMID 30658426, 2019). "Collectively, these results reveal that the IL-6 secreted by CC-MSCs enhances the progression of colorectal cancer cells through IL-6/JAK2/STAT3 signaling, and could provide a novel therapeutic or preventive target." (PMID 29348540, 2018). "Ameliorating the interaction between CC-MSCs and colorectal cancer cells using anti-IL-6 antibodies may offer a novel therapeutic or preventive treatment." (PMID 29348540, 2018). "IL-6’s activation of STAT3 appears to protect the epithelium of the GI tract from apoptosis and stimulates regeneration, and high IL-6 levels have been associated with increased colorectal cancer tumor risk." (PMID 30038723, 2018). "In addition, we show that IL-6 was involved in the development of colorectal cancer in both the APCMin/+ and AOM-DSS mouse models." (PMID 29707119, 2018). "Several studies assessed the relationship between IL-6, pancreatic cancer and colorectal cancer." (PMID 30038723, 2018). "Moreover, IL-6 can act as a paracrine cytokine to promote the proliferation of colorectal cancer cells." (PMID 29348540, 2018). "Similarly, various researchers found an increased blood IL-6 level in individuals with colorectal cancer, while its concentration was directly correlated with colorectal cancer size, stage, metastatic state, and patient survival." (PMID 29662489, 2018). "Interleukin-6 has been shown to be downstream of BK-B2R activation in airway smooth muscle cells, in synovial fibroblasts where it is involved in inflammatory processes, and in colorectal cancer cells promoting cell invasion and migration." (PMID 30619185, 2018). "A higher level of IL-6 is associated with various medical conditions in older adults, including delirium after non-cardiac surgery, colorectal carcinoma and poor prognosis in older adult patients with chronic lymphocytic leukemia." (PMID 30096932, 2018). "In addition, a high level of IL-6 was detected in colorectal carcinoma tissue with liver metastasis." (PMID 29707119, 2018). "Furthermore, miR-34a can suppress tumor progression by inhibiting the IL-6R/STAT3/miR-34a feedback loop and by inhibiting IL-6-induced colorectal cancer cell EMT, invasiveness, and metastasis." (PMID 28441730, 2017). "Serum IL-6 levels positively correlate with progression of human colorectal cancer." (PMID 28505114, 2017). "miR-34a is a regulator of IL-6/STAT3 signaling in colorectal cancer." (PMID 28441730, 2017). "In vitro, IL-6 was shown to stimulate the invasiveness of human colorectal carcinoma cells." (PMID 28632155, 2017). "Similarly, a previous study found a greater effect of an inflammatory marker (IL-6) on colorectal cancer only among lean people." (PMID 27483316, 2016). "Macrophages are critical source of TNFα and, in particular, macrophages that infiltrate the tumor and circulate in colorectal cancer patients are identified as pro-inflammatory, being able to mediate tumor cell killing by the antigen-driven secretion of both IL-6 and TNFα." (PMID 27662661, 2016). "IL-6 expression increased in colorectal carcinoma especially in low grade carcinoma." (PMID 27006530, 2016). "Moreover, Il-6 expression was significantly increased in advanced stage as compared to early stage of gastric cancer and colorectal carcinoma." (PMID 27034885, 2016). "IL-6 is regarded as an important tumor promoting factor in various types of cancers including lymphoma, melanoma as well as breast, ovarian, pancreatic, prostate and colorectal cancers." (PMID 26258407, 2015).
colorectal cancer (continued). "Additionally, the authors show a strong correlation between IL6 presence in the colorectal cancer and EMAST." (PMID 25836926, 2015). "II’yasova and colleagues found that serum IL-6 concentrations were not statistically significantly associated with the risk of colorectal cancer in the Health Aging and Body Composition Cohort." (PMID 26321888, 2015). "The serum levels of inflammatory factors, including TNF-α, IL-8, and IL-6 are elevated in colorectal carcinoma patients, and it has been suggested that increased plasma levels of these cytokines may have a prognostic role." (PMID 26087180, 2015). "Our presurgical analysis shows that some cytokine levels (IL-6, IL-8, IL-1β and TNFα) were significantly higher in plasma of patients affected by colorectal cancer compared to healthy donors and these differences progressively increase in advanced tumor stages." (PMID 24040252, 2013). "However, epidemiological studies of the associations of IL-6 and TNF-α with risks of colorectal cancer or adenoma, precursor lesions of cancer, however, have been inconsistent." (PMID 24235998, 2013). "IL-6 has been shown to be an independent prognostic marker in cancer-specific mortality, including diffuse large-cell lymphoma, metastatic hormone-refractory prostate cancer, and colorectal cancer." (PMID 22514624, 2012). "In addition, significant alterations in the IFNγ and IL-6 gender-specific pathways and IL-10 gender-common pathways were found in colorectal cancer patients." (PMID 22235223, 2011). "Given the inflammatory properties of IL-6, sIL-6R could emerge as an important inflammatory mediator at different stages of colon cancer pathogenesis through IL-6 signalling in colorectal cancer cells." (PMID 20823887, 2010). "We applied the hapConstructor method to a multilocus investigation of candidate genes involved in pro-inflammatory cytokine IL6 production, IKBKB, IL6, and NFKB1 (16 SNPs total) hypothesized to operate together to alter colorectal cancer risk." (PMID 21129206, 2010). "Our data suggest that focusing on IL-6 trans-signaling may lead to new therapeutic approaches to control tumour growth in colorectal carcinomas." (PMID 20823887, 2010). "In colorectal cancer, pro-inflammatory cytokines such as interleukin-1 beta and interleukin-6 may be accountable for the overexpression of Cox-2, important in the early stage and for progression." (PMID 19356222, 2009). "Interleukin-6 (IL-6) is an immunomodulatory cytokine, which also plays a role in growth stimulation, metastasis, and angiogenesis in secondary tumours in a variety of malignancies, including colorectal cancer." (PMID 18205904, 2008). "Upregulation of DDLPS MDM2 by GP130 signal transduction may be facilitated by STAT1 and STAT3 transcription factors, as seen in colorectal cancer where GP130 activation by IL6 cytokine family member leukemia inhibitory factor led to increased MDM2 levels in a STAT3-dependent fashion." (PMID 40961077, 2025). "Notably, the results obtained from immunohistochemical evaluation were further corroborated by in silico analyses of transcriptomic data derived from The Cancer Genome Atlas (TCGA), which confirmed increased IL-6 mRNA expression in colorectal cancer tissue compared to adjacent normal mucosa." (PMID 41007818, 2025). "While it may decrease Glut4 expression, IL-6 nevertheless promotes glucose consumption in mouse adipocytes, as well as mouse macrophages, rat myotubes, and both human skeletal muscle, and colorectal cancer cells." (PMID 39433211, 2025). "Therefore, inhibition of IL-1β, IL-6, and TNF-α may help reduce inflammation associated with colorectal cancer, potentially slowing tumor growth, angiogenesis, and metastasis." (PMID 41463421, 2025). "Similarly, elevated serum levels of IL-6 have been found in colorectal cancer patients." (PMID 38540292, 2024). "Furthermore, it was observed that anti-IL-6 therapy could reverse the resistance to anti-PD-L1 treatment in colorectal cancer cells." (PMID 39690423, 2024).
colorectal cancer (continued). "Intranasal insulin may decrease the risk of POCD and inhibit the elevated serum IL-6, TNF-α, and S100β levels in elderly patients after laparoscopic radical resection of colorectal cancer, which proves that intranasal insulin may be a promising therapeutic option for POCD." (PMID 38915348, 2024). "Thus, the drastic IL-6 surge observed for colorectal cancer patients may reflect the magnitude of the inflammatory response initiated during surgery." (PMID 38067195, 2023). "Here, the main tumor-promoting cytokines released by MDSCs, VEGF, HGF, IL-6, and IL-23 were detected, and the results showed that only IL-23 levels were significantly increased in the supernatant of MDSCs cultured with PA+MC-38-CM as well as in implanted colorectal cancer loaded with P. anaerobius." (PMID 37781363, 2023). "However, other studies have also shown that STAT2 could promote the tumorigenesis of colorectal cancer (CRC) by upregulating the expression of IL-6 and activating the STAT3 signaling pathway." (PMID 34276757, 2021). "Indeed, the suppression of TGF-beta signaling induces IL-6-dependent colorectal cancer cell growth." (PMID 33923292, 2021). "Growing evidence suggests an important role for pro-inflammatory cytokines like the IL-6 gene in the microenvironment of tumor development and regarded as an important tumor promoting factor in various types of human cancers including breast, oral, gastrointestinal, prostate, and, colorectal cancer." (PMID 33684135, 2021). "It has been suggested that IL-6 released during inflammation by tumor epithelial cells and immune cells could cause the hMSH3 shift and EMAST genotype, which has often been associated with poor prognosis in patients with colorectal cancers." (PMID 33923292, 2021). "Experimental and clinical studies demonstrated a clear association of sporadic CRC and inflammation-associated colorectal cancer with IL-6 signaling, although the specific mechanism through which IL-6 plays a role during CRC onset and progression has not been completely clarified." (PMID 33923292, 2021). "Furthermore, it has recently been suggested that IL-6 could promote colorectal cancer progression through the induction of EMT, metastatic cell spread, angiogenesis, self-renewal, and drug resistance." (PMID 33923292, 2021). "Besides, PDCD4 knockout also promoted AOM plus DSS-induced colorectal cancer by the mechanism that PDCD4 deficiency increased the macrophage-secreted IL-6 induced by DSS and elevated the epithelial cell susceptibility to IL-6/STAT3 pathway-mediated cell proliferation during malignant transformation." (PMID 33099584, 2020). "Furthermore, there were several reports that surgical stress and primary tumor resection could be related to metastasis after the operation and the IL-6 and growth hormone were also reported to be closely related to metastases of colorectal cancer." (PMID 32180030, 2020). "We investigated whether metformin treatment suppresses IL-6-induced EMT in colorectal cancer cells." (PMID 30308035, 2018). "To determine whether IL-6 plays an essential role in tumorigenesis of colorectal cancer, we used IL-6tm1Kopf mice, which are IL-6 gene-knockout mice, to generate colorectal neoplasms that result from the inflammatory insult induced by azoxymethane (AOM) and dextran sulfate sodium (DSS)." (PMID 29707119, 2018). "Non-colitis-associated colorectal cancer displays large numbers of inflammation cells within the solid tumor, which causes the production of mutagens (e.g. ROS and NO), tissue injury and pro-inflammatory cytokines, including IL-6." (PMID 30038723, 2018). "Only a recent paper from the Health Professionals Follow-up Study observed a borderline significant increased risk of colorectal cancer with higher IL-6 concentrations, but this association did not remain significant when the first 2 years of follow-up were excluded." (PMID 26321888, 2015).
colorectal cancer (continued). "In addition, the MyD88-dependent pathway of LPS signaling has been suggested to play a potential prognostic role for tumor malignancy in colorectal cancer development, and forced MyD88 expression has been reported to induce the production of inflammatory cytokines such as IL-6 and IL-8." (PMID 25691060, 2015). "Interestingly IL-6 was previously reported to be associated with variations in the SLC6A4 gene (see the previous paragraph), which also seems to be a mediator of tumor progression in colorectal cancer." (PMID 22911682, 2012). "Therefore, the differences observed between colon adenoma and colorectal cancer patients confirm that the IFNy production pathway for immune response homeostasis is specific to men, while the IL-6 production pathway for immune response homeostasis is specific to women." (PMID 22235223, 2011). "Furthermore, given that C-reactive protein concentrations are primarily determined by interleukin-6 concentrations, it is of interest that recent studies have shown that increased circulating concentrations of interleukin-6 in colorectal cancer are related to its production by the tumour." (PMID 12915865, 2003). "Meanwhile, IL-6 induced chemotherapeutic resistance by activating autophagy via IL-6/JAK2/BECN1 signaling pathway, as seen in colorectal cancer." (PMID 40160826, 2025). "IL-6 promotes tumorigenesis via the STAT pathway in cancers such as breast, lung, and colorectal cancer." (PMID 41311372, 2025). "Inflammation-related plasma proteins such as C-reactive protein (CRP), IL-6 (interleukin-6), TNF-alpha (tumor necrosis factor) and its receptors, adiponectin play complex roles in colorectal cancer development." (PMID 41464635, 2025). "In colorectal cancer, lactate produced by tumors induces H3K18 lactylation, inhibits retinoic acid receptor gamma (RARγ) transcription in macrophages, increases IL‐6 levels, and enhances tumor‐promoting functions." (PMID 40692663, 2025). "In this study, we aimed to investigate the expression patterns and potential clinical significance of IL-6 and RBP4 in colorectal cancer." (PMID 41007818, 2025). "Treatment with IL-6 promotes expression of the glycolytic genes SLC2A1, HK2, PKM2, PFKFB3, and LDHA in human colorectal cancer cells, and similarly induces Hk2, Pkm2, and Pfkfb3 expression in murine macrophages." (PMID 39433211, 2025). "STAT3 is also activated in colorectal cancer (CRC) and promotes tumor growth and progression in conjunction with the IL-6 signaling pathway." (PMID 39995416, 2025). "Preclinical models have demonstrated that TAMs secrete IL-6, which drives chemoresistance through IL-6R/STAT3 signaling; for example, in colorectal cancer, TAM-derived IL-6 confers resistance to 5-fluorouracil (5-FU)." (PMID 41058699, 2025). "On the other hand, LPS induces pro-inflammatory cytokines (such as IL-1β, IL-6, and TNF-α) in a HMGB1-dependent manner to improve colorectal cancer progression." (PMID 40495163, 2025). "We found that knockout of NSD2 significantly reduced the concentrations of IL‐6, TNF‐α, and TGF‐β1 in the serum of mice with colorectal cancer." (PMID 38400589, 2025). "In another study that analyzed surgical specimens from colorectal cancer patients, the pre-operative CT showed that VAT HU was significantly positively correlated with the degree of IL-6 expression in the VAT." (PMID 39858017, 2025). "This study provides comprehensive insights into the role of IL-6 and RBP4 in colorectal cancer (CRC)." (PMID 41007818, 2025). "IL-6, IL-1β, IL-10, IL-17, and TNF-α were selected as key mediators of inflammation and immune regulation in colorectal cancer." (PMID 41267807, 2025). "For example, TAMs have been shown to regulate the IL-6/JAK2/STAT3/miR-506-3p/FoxQ1 axis, which enhances colorectal cancer (CRC) motility and invasion through the induction of EMT and upregulation of CCL2, promoting macrophage recruitment." (PMID 40083697, 2025).